NAA30 (N-alpha-acetyltransferase 30, NatC catalytic subunit)
Description:
Catalytic subunit of the N-terminal acetyltransferase C (NatC) complex. Catalyzes acetylation of the N-terminal methionine residues of peptides beginning with Met-Leu-Ala and Met-Leu-Gly. N-terminal acetylation protects proteins from ubiquitination and degradation by the N-end rule pathway. Necessary for the lysosomal localization and function of ARL8B sugeesting that ARL8B is a NatC substrate.
Synonyms: C14orf35; MAK3; NAT12; FLJ35355; Mak3p; NAT12P
Tractability: Small molecule: a structure with a bound ligand is known. PROTAC: ubiquitination databases record sites on it; its protein half-life has been measured.
Gene: Protein-coding gene on chromosome 14 (57,390,544 to 57,415,906, forward strand). Ensembl gene ENSG00000139977.
Subcellular location: Cytoplasm; Nucleus
Subcellular location (Human Protein Atlas): Cytosol
Pathways (Reactome):
Vesicle-mediated transport: Retrograde transport at the Trans-Golgi-Network
Gene Ontology:
Molecular function: protein binding; protein-N-terminal amino-acid acetyltransferase activity; acyltransferase activity, transferring groups other than amino-acyl groups; protein N-terminal-methionine acetyltransferase activity
Biological process: protein stabilization
Cellular component: cytoplasm; cytosol; NatC complex; nucleus
Genetic constraint (gnomAD): Loss-of-function variants: 5 observed, 26.33 expected, observed/expected ratio (o/e) 0.19, 90% interval 0.098 to 0.4. The upper end of that interval is the gene's LOEUF score, 0.4, which puts it in group 1 of 6, group 1 being the genes least tolerant of losing a copy. Missense variants: 409 observed, 463.94 expected, observed/expected ratio (o/e) 0.88, 90% interval 0.81 to 0.96. Synonymous variants: 215 observed, 203.59 expected, observed/expected ratio (o/e) 1.06, 90% interval 0.94 to 1.18.
Homologues: Orthologues: chimpanzee NAA30 (99% identical), macaque NAA30 (98% identical), dog NAA30 (95% identical), pig NAA30 (93% identical), rat Naa30 (87% identical), mouse Naa30 (86% identical), rabbit NAA30 (83% identical), tropical clawed frog naa30 (58% identical), zebrafish naa30 (52% identical), Drosophila melanogaster Naa30A (40% identical), Caenorhabditis elegans natc-2 (30% identical), Drosophila melanogaster Naa30B (25% identical). Paralogues in human: NAA10 (15% identical), NAA11 (14% identical), NAA20 (12% identical), NAA50 (10% identical).
Diseases named in the same sentence as NAA30 in open-access papers:
NAA30 is named in the same sentence as 6 diseases in open-access papers, as found by Europe PMC text mining. Sharing a sentence is not in itself a finding about the gene and the disease. The quoted sentences say what the papers report.
glioblastoma (4 papers, 2015 to 2023). The most malignant astrocytic tumor (WHO grade IV). "However, in another published study comparing normal with glioblastoma tissues, NAA30 and NAA80, which are associated with improved survival are downregulated, while NAA15, which is associated with worse survival, is upregulated." (PMID 32942614, 2020). "A strong upregulation of NAA30 has been observed in glioblastoma, and a NAA30-knockdown in glioblastoma-initiating cells (GICs) reduced their viability, sphere-forming ability, and hypoxia tolerance." (PMID 33139728, 2020). "Furthermore, in glioblastoma-initiating cells (GICs), that drive tumorigenesis of the most common primary brain malignancy, a strong overexpression of the protein Naa30 was detected." (PMID 37585488, 2023).
breast carcinoma (1 paper, 2023). "We further confirmed reduced protein levels of selected NatC substrates in an independent NAA30-KO breast cancer cell line." (PMID 37891180, 2023). "The effect on EEA1 and p62 was confirmed in an independent NAA30-KO breast cancer cell line." (PMID 37891180, 2023).
glioma (1 paper, 2015). A benign or malignant brain and spinal cord tumor that arises from glial cells (astrocytes, oligodendrocytes, ependymal cells). "Interestingly, the 3’UTR of NAT12/NAA30 seemed to be universally down-regulated in glioma tissue samples." (PMID 26292663, 2015). "Glioma patients with decreased expression of the distal 3’UTR end of the NAT12/NAA30 transcript (Probe: 225679_at) had significantly shorter survival, while the increased expression of the coding regions of this gene (Probes: 228322_at, 228321_at) did not seem to correlate with patient survival." (PMID 26292663, 2015). "Also, shorter 3’UTR of NAT12/NAA30 correlated with poor survival in glioma patients." (PMID 26292663, 2015).
cancer (5 papers, 2019 to 2023). A tumor composed of atypical neoplastic, often pleomorphic cells that invade other tissues. "Interestingly, most of these genes are linked with cancer processes (Pld1, Fam13c, Svbp, TMem192, Zc3h7a, RTP4, Naa30, Zgrf1, Slc33a1, Dnmt3b, Map6, Plin4, Eps8L2, Alg12, Capg and Tdp2)." (PMID 37700325, 2023). "Overexpression of the NatC catalytic subunit NAA30 increases cancer cell viability." (PMID 33126484, 2020). "shRNA-mediated knockdown of NAA30 gene in GICs demonstrated that NatC may serve as a therapeutic target in these types of cancer, as intracranial transplantation of such NatC depleted cells resulted in prolonged animal survival compared to control mice transplanted with unmodified GICs." (PMID 37585488, 2023). "Finally, NAA30 and NAA40 were essential to some, but not all, cancer cells, indicating that their targeting could be particularly effective in specific genetic or transcriptomic contexts." (PMID 32942614, 2020).
tumor (1 paper, 2015). "To investigate the expression of NAT12/NAA30 in GBM tumor biopsies, normal human brain, NSCs, GICs and NFCs we used microarrays, real-time quantitative reverse-transcription PCR (qPCR), western blots, immunolabeling and public data mining." (PMID 26292663, 2015). "To investigate the effect of NAT12/NAA30 knockdown on GIC growth and tumor formation in vivo we used a robust orthotopic xenograft model." (PMID 26292663, 2015). "Since GICs are believed to reside in the perivascular niche of the tumor, our immunolabeling might indicate that NAT12/NAA30 is predominantly expressed in an immature cell types in GBM." (PMID 26292663, 2015).
NAA30 also shares sentences with these, for which no sentence is quoted: lung adenocarcinoma (1 paper).